PDK3 (pyruvate dehydrogenase kinase 3)
Description:
Inhibits pyruvate dehydrogenase activity by phosphorylation of the E1 subunit PDHA1, and thereby regulates glucose metabolism and aerobic respiration. Can also phosphorylate PDHA2. Decreases glucose utilization and increases fat metabolism in response to prolonged fasting, and as adaptation to a high-fat diet. Plays a role in glucose homeostasis and in maintaining normal blood glucose levels in function of nutrient levels and under starvation. Plays a role in the generation of reactive oxygen species.
Synonyms: CMTX6; GS1-358P8.4
Tractability: Small molecule: an approved drug acts on it; a structure with a bound ligand is known; a high-quality ligand is known. PROTAC: it is named in the literature on targeted protein degradation; ubiquitination databases record sites on it; its protein half-life has been measured; a small molecule that binds it is known.
Target class: Kinase; Enzyme; Atypical protein kinase PDHK subfamily; Atypical protein kinase group; Protein Kinase
Gene: Protein-coding gene on chromosome X (24,465,244 to 24,550,466, forward strand). Ensembl gene ENSG00000067992.
Subcellular location: Mitochondrion matrix
Subcellular location (Human Protein Atlas): Mitochondria; Nucleoli
Pathways (Reactome):
Metabolism: Regulation of pyruvate dehydrogenase (PDH) complex
Signal Transduction: Signaling by Retinoic Acid
Gene Ontology:
Molecular function: ATP binding; protein binding; protein kinase activity; protein serine/threonine kinase activity; pyruvate dehydrogenase (acetyl-transferring) kinase activity
Biological process: cellular response to fatty acid; hypoxia-inducible factor-1alpha signaling pathway; peptidyl-serine phosphorylation; peroxisome proliferator activated receptor signaling pathway; regulation of glucose metabolic process; regulation of pyruvate decarboxylation to acetyl-CoA; regulation of reactive oxygen species metabolic process; cellular response to stress
Cellular component: mitochondrion; mitochondrial matrix
Gene-disease validity (ClinGen):
ClinGen rates the evidence that PDK3 causes each of these diseases.
Charcot-Marie-Tooth disease X-linked dominant 6 (X-linked): Definitive.
Homologues: Orthologues: macaque PDK3 (100% identical), chimpanzee PDK3 (99% identical), pig PDK3 (99% identical), rabbit PDK3 (99% identical), dog PDK3 (99% identical), rat Pdk3 (98% identical), mouse Pdk3 (97% identical), guinea pig PDK3 (96% identical), tropical clawed frog pdk3 (85% identical), zebrafish pdk3a (82% identical), Drosophila melanogaster Pdk (58% identical), Caenorhabditis elegans pdhk-2 (51% identical), and 1 more. Paralogues in human: PDK1 (68% identical), PDK2 (67% identical), PDK4 (62% identical), BCKDK (29% identical).
Diseases named in the same sentence as PDK3 in open-access papers:
PDK3 is named in the same sentence as 57 diseases in open-access papers, as found by Europe PMC text mining. Sharing a sentence is not in itself a finding about the gene and the disease. The quoted sentences say what the papers report.
gastric cancer (7 papers, 2019 to 2024). A primary or metastatic malignant neoplasm involving the stomach. "PDK3 knockdown suppressed proliferation and caused apoptosis in gastric cancer cell lines and the prostate cancer cell line." (PMID 34589439, 2021). "Furthermore, higher PDK3 expression has been associated with chemoresistance in gastric cancer cells and colon cancer cells." (PMID 34589439, 2021). "In the study of chemoresistance in gastric cancer, PDK3 is highly expressed to promote glycolysis in chemoresistant cancer cells." (PMID 34220962, 2021). "Over-expression of PDK3 reversed the suppressive effect of miR-497-5p on gastric cancer cell proliferation." (PMID 31409724, 2019). "Our results indicated that PDK3 was the downstream target for miR-497-5p and a potential oncogene in gastric cancer." (PMID 31409724, 2019). "Similarly, HSF1 stimulates the expression of pyruvate dehydrogenase kinase 3 (PDK3), which promotes glycolysis that supports cancer progression and chemoresistance in gastric cancer cells." (PMID 37153737, 2023). "Therefore, HSF1 and PDK3 promote glycolysis and chemoresistance in gastric cancer through a positive feedback loop." (PMID 34064083, 2021). "In chemoresistant gastric cancer (GC) cells and gastric cancer tissues, PDK3 is highly expressed." (PMID 33739396, 2021). "PDK3 knockdown reduced the viability of gastric cancer cells with silenced miR-497-5p." (PMID 31409724, 2019). "Nevertheless, the involvement of PDK3 in gastric cancer remains to be determined." (PMID 31409724, 2019). "Importantly, PDK3 was highly expressed in gastric cancer tissues based on the TCGA database and our immunohistochemical staining." (PMID 31409724, 2019). "Our study proposed the miR-497-5p/PDK3 as a potential therapeutic target for gastric cancer." (PMID 31409724, 2019). "In chemo-resistant gastric cancer cells, HSF1 promotes the transcription of pyruvate dehydrogenase kinase 3 (PDK3)." (PMID 34064083, 2021).
prostate carcinoma (7 papers, 2021 to 2026). A carcinoma that arises from epithelial cells of the prostate gland. "The histone lysine demethylase KDM4A serves as a coactivator for E2F1, binding to the promoters of PDK1 and PDK3, thus influencing the metabolic transition between glycolysis and mitochondrial oxidation in prostate cancer." (PMID 41158756, 2026). "KDM4A-E2F1 complex regulates metabolism by upregulating pyruvate dehydrogenase kinase 1 (PDK1) and pyruvate dehydrogenase kinase 3 (PDK3), thereby promoting the switch of oxidative phosphorylation to glycolytic metabolism in prostate cancer cells." (PMID 35689245, 2022). "By contrast, in prostate cancer cells, MALAT1 silencing downregulates ME3, PDK1, PDK3, and choline kinase—enzymes critical for OXPHOS." (PMID 41199749, 2025). "Correlation between clinical and pathological variables and PDK1, PDK2, PDK3 and PDK4 protein expression in prostate cancer." (PMID 35692804, 2022). "Pyruvate dehydrogenase kinases such as PDK3 and PDK4 are important markers in glycolysis, have been reported to be used to predict the recurrence in prostate cancer, this might be relevant with the elevated level of lactate and the activation of TNF pathway." (PMID 39811936, 2025).
melanoma (6 papers, 2014 to 2025). A malignant, usually aggressive tumor composed of atypical, neoplastic melanocytes. "Both activated VEGFR2 via the pro-oncogenic R1051Q mutation and the HIF-1/PDK3 bioenergetic pathway induce relevant metabolic changes in melanoma cells, serving as new targets for therapeutic intervention in melanoma." (PMID 35311151, 2022). "The use of dichloroacetate to inhibit pyruvate dehydrogenase kinase-3 (PDK3) increased the levels of ROS and sensitivity to ES in melanoma cells." (PMID 39970778, 2025). "In melanoma, inhibition of PDK3 activity by dichloroacetate enhances the antitumor effects of elesclomol." (PMID 31409724, 2019). "Similarly, DCA was reported to inhibit PDK3 in melanoma cells." (PMID 38069413, 2023). "Indeed, exposure to DCA, or knock-down of PDK3 with siRNA, has been shown to potentiate elesclomol’s induction of oxidative stress in melanoma cell lines, and concurrent treatment with DCA amplified the growth retardation of a human melanoma achieved with elesclomol in nude mice." (PMID 25279352, 2014).
breast carcinoma (5 papers, 2018 to 2025). "Notably, PDK3 expression is elevated in breast cancer tissues, akin to PDK1, and is induced by HIF-1α, exhibiting increased expression levels." (PMID 41465397, 2025). "However, the specific biological functions of SMS, PAFAH1B2, or PDK3 need to be further investigated in breast cancer." (PMID 33494814, 2021). "Notably, the upregulation of PDK1 and PDK3 in breast cancer patients could be correlated with higher Ragnum and Buffa hypoxic scores." (PMID 33316932, 2020). "The overall survival rates of breast cancer patients based on the expression of these three genes (SMS, PAFAH1B2 and PDK3) were analyzed by UCSC Xena (data retrieved on November 24, 2020)." (PMID 33494814, 2021). "In the current study, we found that mRNA levels for two of the four PDK isoforms (PDK1 and PDK3) are upregulated in the TNBC and basal-like breast cancer subtypes." (PMID 33316932, 2020). "We showed a significant gain (p < 0.0001) in the expression of PDK1 and PDK3 in TNBC versus non-TNBC and in basal-like breast cancers relative to other subtypes such as luminal A, luminal B and HER2-enriched breast cancers." (PMID 33316932, 2020).
colon cancer (5 papers, 2015 to 2021). "It is reported that the overexpression of PDK3 is positively associated with severity of cancer and negatively associated with disease-free survival in colon cancer patients." (PMID 26616174, 2015). "In colon cancer cell lines, PDK3 expression is controlled by HIF-1α and contributes to hypoxia-induced increased drug resistance." (PMID 33739396, 2021). "Overexpression of PDK3 and PDK4 was shown to be associated with drug resistance and early recurrence in colon cancer cells." (PMID 28505181, 2017). "Similarly, overexpression of pyruvate dehydrogenase kinase 3 (PDK3) promotes a metabolic switch from mitochondrial respiration to glycolysis under hypoxia condition and increases drug resistance in cervical and colon cancer." (PMID 29489864, 2018). "Moreover, the expression of PDK3 is controlled by HIF-1αand contributes to hypoxia-induced drug resistance in colon cancer cells." (PMID 26616174, 2015). "In colon cancer, PDK3 is markedly increased compared to that in adjacent normal tissues and PDK3 levels are positively associated with severity of cancer and negatively associated with disease-free survival." (PMID 33739396, 2021).
glioma (5 papers, 2017 to 2023). A benign or malignant brain and spinal cord tumor that arises from glial cells (astrocytes, oligodendrocytes, ependymal cells). "In gliomas, DLEU2 regulates PDK3 expression and glioma progression in an miR-186-5p dependent manner." (PMID 37095423, 2023). "For example, lncRNA MALAT1/miR-199a/ZHX1 axis suppresses glioblastoma proliferation and progression, and lncRNA-DLEU2/miR-186-5p/PDK3 axis advances glioma cell progression." (PMID 34459789, 2021). "In IDH1WT glioma, we observed higher expression of regulator genes PDK1 and PDK3 as compared to IDH1MUT glioma." (PMID 28467784, 2017). "Under short‐term treatment conditions compared to vehicle‐treated control cells, glioma cells exhibited minimal or no change in PDK1, PDK2, PDK3, and PDK4 protein expression." (PMID 34058053, 2022).
diabetes (4 papers, 2019 to 2025). "Notably, because PDK3 is shared between pGDM and T2D, it could serve as a biomarker for diabetes development." (PMID 40868918, 2025). "Notably, the regulation of Pdk3 expression in the liver has remained largely unknown because its expression is almost undetectable under normal conditions, as well as during starvation and diabetes, in both humans and rodents." (PMID 40275022, 2025). "For instance, PDK4 is involved in metabolic changes under high-fat diet condition and diabetes, while PDK1 and PDK3 are more likely to contribute to metabolic switch and cell survival under hypoxia." (PMID 31409724, 2019).
glioblastoma (4 papers, 2019 to 2025). The most malignant astrocytic tumor (WHO grade IV). "As an oncogene in glioblastoma, PDK3 promotes glioblastoma cell progression." (PMID 40286187, 2025). "Silencing of PDK3 induces the cell death of glioblastoma multiforme." (PMID 31409724, 2019). "Furthermore, the oncogenic role of PDK3 is also found in other cancer types, such as acute myeloid leukemia, glioblastoma and lung cancer." (PMID 31409724, 2019).
Charcot-Marie-Tooth disease (3 papers, 2015 to 2023). An inherited degenerative disorder involving the peripheral nerves. "Recently, a mutation conferring PDK3 hyperactivity has been reported as a cause of Charcot-Marie-Tooth disease and by inhibition of PDK3 activity, phenylbutyrate may prevent PDHC hyper-phosphorylation that has been recognized as the underlying cause of peripheral neuropathy." (PMID 25601413, 2015). "This review considers the enzymes encoded by the DHTKD1, PDK3 and PDXK genes, whose mutations are observed in patients with Charcot-Marie-Tooth (CMT) disease." (PMID 37508330, 2023). "However, the patient (ASD-38) reported here to carry PDK3 splice site variant is not affected with Charcot-Marie-Tooth disease, nor does he suffer from any type of neuropathy." (PMID 28720891, 2017).
colorectal cancer (3 papers, 2020 to 2026). A primary or metastatic malignant neoplasm that affects the colon or rectum. "The non-SMC condensin II complex subunit D3 elevates E2F1 levels and enhances its recruitment to the promoter regions of PDK1 and PDK3, inhibiting pyruvate dehydrogenase activity and the tricarboxylic acid cycle in colorectal cancer." (PMID 41158756, 2026). "Moreover, hypoxia-mediated enhanced expression of PDK3 inhibited drug-induced apoptosis, thus conferring drug resistance in colorectal cancer cell lines (HCT116 and HT29)." (PMID 32806533, 2020). "However, in colorectal cancer tissue, PDK1 had no role, but its PDK3 isoform was associated with cancer progression." (PMID 32806533, 2020).
hepatocellular carcinoma (3 papers, 2020 to 2025). A malignant tumor that arises from hepatocytes. "In alignment with this, PDK3 is the only isoform whose elevated expression was significantly associated with reduced survival in people with hepatocellular carcinoma." (PMID 40275022, 2025). "To explore the adverse effects of hepatic PDK3 upregulation, we analysed transcriptomic data from the Hepatocellular Carcinoma cohort of 372 participants in the PanCancer Atlas of The Cancer Genome Atlas (TCGA) Program75,76." (PMID 40275022, 2025).
lung carcinoma (3 papers, 2020 to 2023). "All these observations suggested the implication of hordenine in the therapeutic management of lung cancer and other PDK3 associated diseases." (PMID 32422877, 2020). "Hordenine can also be used as a potential pyruvate dehydrogenase kinase 3 (PDK3) inhibitor of great value in the treatment of lung cancer." (PMID 36771401, 2023). "Because of its potential therapeutic effect in lung cancer therapy, PDK3 inhibitors have recently been considered a potential target for much research." (PMID 36559012, 2022). "Design and development of potential pyruvate dehydrogenase kinase 3 (PDK3) inhibitors have gained attention because of their possible therapeutic uses in lung cancer therapy." (PMID 32422877, 2020). "In summary, our findings provide the basis for the therapeutic implication of hordenine and its derivatives in lung cancer and PDK3-related diseases after required in vivo validation." (PMID 32422877, 2020). "We have established that hordenine may be exploited as a novel scaffold to inhibit the kinase activity of PDK3 along with a considerable cytotoxic effect on lung cancer cell lines." (PMID 32422877, 2020). "The results suggested that polyphenolic compounds of the C. macrocarpa polar fractions with elevated pose score could be used as a potential treatment for lung cancer or as a scaffold for developing new inhibitors for enzymes HDAC6 and PDK3, related to lung cancer progression." (PMID 36559012, 2022). "Furthermore, it has become more apparent how HDAC6 and PDK3 contribute to the development of lung cancer, and it is now generally accepted that the inhibitors may be used to treat lung cancer." (PMID 36559012, 2022). "It is worth noting that it is now widely accepted that pyruvate dehydrogenase kinase 3 (PDK3) and histone deacetylase 6 (HDAC6) inhibitors can be used to treat lung cancer." (PMID 36559012, 2022).
lactic acidosis (2 papers, 2022 to 2023). Metabolic acidosis characterized by the accumulation of lactate in the body. "Variants in all subunits of the PDC and in PDK3 have been reported, with varying phenotypes including lactic acidosis, neurodevelopmental delay, peripheral neuropathy, or seizures." (PMID 36551928, 2022).
oral cancer (2 papers, 2019 to 2021). "Treatment with BME on oral cancer cell lines significantly reduced mRNA and protein expression levels of key glycolytic genes SLC2A1 (GLUT-1), PFKP, LDHA, PKM and PDK3." (PMID 31638999, 2019).
pancreatic cancer (2 papers, 2022 to 2023). "The IHC results showed that PDK3 was highly expressed in pancreatic cancer tissues compared with matched normal tissues." (PMID 36369467, 2022). "E2F1, which was preferentially essential in pancreatic cancer cells, has been previously shown to regulate both pancreatic B-cell development and cancer growth by increasing the expression of PDK1 and PDK3 which results in increased aerobic glycolysis and growth in pancreatic cancers." (PMID 36727483, 2023). "Nevertheless, the function of PDK3 in pancreatic cancer has not been determined." (PMID 36369467, 2022).
renal pelvis tumor (2 papers, 2021 to 2024). "PDK3 overexpression was proved to be strongly correlated with a high tumor stage and grade, vascular invasion, renal pelvis tumors and high mitotic rate." (PMID 39272712, 2024).
Sepsis (2 papers, 2025). Sepsis is defined as life-threatening organ dysfunction caused by a dysregulated host response to infection. "Gene expressions of enzymes of the pyruvate dehydrogenase complex (Pdha1, Pdhb) were unaffected or decreased throughout sepsis, whereas pyruvate dehydrogenase kinase 3 (Pdk3), but not 1 (Pdk1), was upregulated." (PMID 39821755, 2025).
acute myeloid leukemia (1 paper, 2019). Acute myeloid leukemia (AML) is a group of neoplasms arising from precursor cells committed to the myeloid cell-line differentiation. "Over-expression of PDK3 is correlated with poor prognosis of acute myeloid leukemia." (PMID 31409724, 2019).
adenosquamous cell carcinoma (1 paper, 2024). "Compared with those of other histological types, adenosquamous cell carcinoma samples showed significantly elevated expression of PDK3." (PMID 38400534, 2024).
Alzheimer disease (1 paper, 2024). A progressive, neurodegenerative disease characterized by loss of function and death of nerve cells in several areas of the brain leading to loss of cognitive function such as memory and language. "There are also studies on the relationship between genes and cognitive function that show that five genes, PFKFB4, PDK3, KIAA0319L, CEBPD, and PHC2T, have the potential to recognize Alzheimer’s disease." (PMID 39328989, 2024).
bladder cancer (1 paper, 2023). "EA exhibits in vitro and in vivo anti-tumor activity for human bladder cancer.Inhibits tumor cell proliferation; migration and invasion.Down-regulation of PD-L1 and reduction of angiogenesis.Inhibition of kinase-related pathways such as PI3K/AKT, PDK3, and SPHK." (PMID 37049544, 2023).
brain injuries (1 paper, 2022). "It has been reported that determine pyruvate dehydrogenase (PDH) is important for the changes in brain energy metabolism seen in various brain injuries, and DCA, a structural analogue of pyruvate, is attached to the pyruvate binding site to inhibit PDK in the order of PDK2 > PDK1, PDK4 > PDK3." (PMID 36432491, 2022).
Cachexia (1 paper, 2025). Severe weight loss, wasting of muscle, loss of appetite, and general debility related to a chronic disease. "Next, we hypothesized that the cachexia-related expression of Pck1 and Pdk3 in CACS KL mice is regulated through the same IL-6–JAK–STAT signalling mechanism." (PMID 40275022, 2025). "Identifying a downstream target of IL-6 signalling, such as PDK3, could provide a way to uncouple therapeutic effects from unwanted side effects, potentially offering a more effective treatment for the deregulated metabolic processes observed in cachexia." (PMID 40275022, 2025). "Similarly, in mouse cancer cachexia models, we observe IL-6–JAK–STAT-signalling-mediated induction of Pck1 and Pdk3 expression in the liver." (PMID 40275022, 2025).
Charcot-Marie-Tooth neuropathy (1 paper, 2020). "Variants in PDK3 induces an X-linked Charcot-Marie-Tooth neuropathy." (PMID 33426505, 2020).